SIRT4 (sirtuin 4)
Diseases named in the same sentence as SIRT4 in open-access papers (continued):
Sharing a sentence is not in itself a finding about the gene and the disease.
bladder cancer (5 papers, 2019 to 2025). "In bladder cancer, SIRT4 regulates the chemotaxis and cytotoxicity of CD8+ T cells, whereas its inhibition leads to immune evasion and tumor development." (PMID 41425553, 2025). "It is particularly important to note here that SIRT4 level, T stage and AJCC stage were all prognostic factors for bladder cancer in our univariate survival analysis, whereas the multifactorial analysis showed that SIRT4 was an independent prognostic factor." (PMID 37301821, 2023). "Our results suggest that SIRT4 inhibits the growth of bladder cancer cells by suppressing autophagy." (PMID 37301821, 2023). "There existed a clear inverse relationship between the expression levels of miR-424 and pro-apoptotic UNC5B or SIRT4 in bladder cancer tissues." (PMID 32522234, 2020). "CDDP-mediated suppression of xenograft bladder tumor growth was prohibited by the addition of miR-424, whereas ectopic expression of UNC5B or SIRT4 partially restored miR-424-dependent decrease in CDDP sensitivity of bladder cancer 5637 and T24 cells." (PMID 32522234, 2020). "In the present study, we have described for the first time that HIF-1α-mediated induction of miR-424 causes down-regulation of pro-apoptotic UNC5B and SIRT4, thereby inhibiting CDDP-dependent apoptotic cell death of bladder cancer cells." (PMID 32522234, 2020). "Therapeutic approaches involving the selective modulation of SIRT activity are likely to enhance CD8+ T cell responses, either by inhibition—for example, SIRT2 and SIRT5 in LUAD, or by activation—for instance, SIRT4 in bladder cancer—to overcome resistance to immunotherapy." (PMID 41425553, 2025). "Next, we asked whether there could exist the correlation between miR-424 and UNC5B or SIRT4 expression levels in our bladder cancer samples (n = 30)." (PMID 32522234, 2020). "In contrast, the SIRT4 mitochondrial family member can repress tumor formation, with its mRNA expression levels being notably reduced (relative to normal tissues) in a number of malignancies, including bladder cancer, therefore rendering SIRT4 a promising druggable biomarker for the disease." (PMID 30875794, 2019). "Together, these results suggest that SIRT4 may be involved in the development of bladder cancer." (PMID 37301821, 2023). "Therefore, we wanted to further explore the functional role of SIRT4 in bladder cancer." (PMID 37301821, 2023). "Additionally, siRNA-mediated silencing of either UNC5B or SIRT4 resulted in a significant decrease in the sensitivity to CDDP of bladder cancer 5637 and T24 cells, whereas miR-424-mediated decrease in CDDP sensitivity was partially restored by forced expression of UNC5B or SIRT4." (PMID 32522234, 2020). "Inverse correlations between miR-424 and UNC5B or SIRT4 expression levels in bladder cancer tissues further supported the negative regulation of UNC5B and SIRT4 by miR-424 in vivo." (PMID 32522234, 2020). "Based on our present results, forced expression of miR-424 mimics reduced UNC5B and SIRT4 expressions in bladder cancer 5637 and T24 cells, whereas miR-424 inhibitor increased UNC5B and SIRT4 expressions in these cells." (PMID 32522234, 2020). "In the current study, we have found for the first time that miR-424, a direct target of HIF-1α, decreases CDDP sensitivity of bladder cancer cells through down-regulation of pro-apoptotic UNC5B and SIRT4." (PMID 32522234, 2020). "Collectively, these results indicate that miR-424 suppresses CDDP-mediated bladder cancer cell death through down-regulation of UNC5B and SIRT4 in vivo." (PMID 32522234, 2020). "Until recently, the relationship between SIRT4 and autophagy has not been investigated in bladder cancer." (PMID 37301821, 2023). "However, the role of SIRT4 in bladder cancer has not been clarified." (PMID 37301821, 2023). "Therefore, it is suggestive that HIF-1α/miR-424/UNC5B/SIRT4 regulatory axis contributes to the acquisition and/or the maintenance of CDDP resistance of bladder cancer cells irrespective of hypoxia." (PMID 32522234, 2020).
gastric cancer (5 papers, 2017 to 2023). A primary or metastatic malignant neoplasm involving the stomach. "SIRT4 can induce G1 cell cycle arrest by inhibiting phosphorylated extracellular signal-regulated kinase, cyclin D and cyclin E in gastric cancer." (PMID 31817470, 2019). "The results suggested that SIRT4, SIRT6, and SIRT7 were associated with Lauren classification and SIRT3-5 were associated with pStage in gastric cancer." (PMID 29088792, 2017). "We detected the mRNA expression level of three gastric cancer biomarkers, chloride channel-3 (CLC-3), slingshot protein phosphatase 1 (SSH1), and sirtuin 4 (SIRT4) in Cul30-GES-1 and B-GES-1 cells." (PMID 33194715, 2020). "A seemingly important part of gastric cancer (GC), SIRT4, is involved in regulating EMT." (PMID 31817470, 2019).
Hypertension (5 papers, 2018 to 2026). The presence of chronic increased pressure in the systemic arterial system. "In this work, we observed, for the first time, that that maternal melatonin therapy prevents hypertension associated with increased expression of Sirt1, Sirt4, Prkaa2, Prkab2, Pparg, and Ppargc1a in adult offspring kidneys." (PMID 29641494, 2018). "The level of Sirt4 protein is decreased in the brains of aged rats as well, which further indicated the role of Sirt4 in hypertension related aging." (PMID 41507140, 2026). "Several nutrient-sensing signals are involved in high-fructose and high-fat-induced hypertension, such as SIRT4, AMPKα2, PPARs, and PGC-1α." (PMID 29315230, 2018). "Belonging to the Sirtuins (Sirt) family as well, Sirt4 expression was upregulated following melatonin administration in rat fetal hypertension, suggesting that Sirt4 might be involved in mitigating the onset and progression of hypertension." (PMID 41507140, 2026). "Thus, one might expect that high-fructose and high-fat diets reduced SIRT4 and AMPKα2, via increased oxidative stress in a way that programs the development of hypertension." (PMID 29315230, 2018). "In contrast, prenatal metformin therapy did not activate but rather inhibited AMPK-related nutrient sensing signals, including AMPKs, SIRT1, SIRT4, PPARs, and PGC-1α, by which it protects adult male offspring against hypertension." (PMID 29614026, 2018). "In addition, the novel role of Sirt1, Sirt4 and ANXA1 in hypertension related bone marrow microvascular ageing deserves further study." (PMID 41507140, 2026). "It is noteworthy that neither the knockout nor the overexpression of SIRT4 alters baseline blood pressure or prevents Ang II‐induced hypertension, suggesting that SIRT4 may have no impact on vascular aging and remodeling." (PMID 41180381, 2025).
osteoarthritis (5 papers, 2023 to 2024). A noninflammatory degenerative joint disease occurring chiefly in older persons, characterized by degeneration of the articular cartilage, hypertrophy of bone at the margins and changes in the synovial membrane. "Studies were also performed on the effects of SIRT4 on human cartilage cells from osteoarthritis patients." (PMID 36675041, 2023). "SIRT4 overexpression has been shown to increase TNF-α and IL-6 secretion and accelerate bone destruction in patients with osteoarthritis." (PMID 36675041, 2023). "The role of SIRT4 in RA has not been studied, but SIRT4 can affect osteoarthritis through a variety of inflammatory factors, such as TNFα and IL-6, and the effect of SIRT4 on oxidative stress has also been proven the increased expression of SIRT4 can up-regulate SOD1, SOD2, and catalase." (PMID 37238636, 2023).
renal fibrosis (5 papers, 2022 to 2025). A final common manifestation of a wide variety of chronic kidney diseases characterized by glomerulosclerosis and tubulointerstitial fibrosis. "Overall, our study revealed that SIRT4 inhibition can alleviate the progression of renal fibrosis by suppressing CCN2 expression." (PMID 39495216, 2024). "Together, these data support that SIRT4-mediated deacetylation of U2AF2 at K413 is an important step in SIRT4-induced renal fibrosis." (PMID 39495216, 2024). "Knockout of Sirt4 or targeted deletion of Sirt4 in renal TECs alleviates renal fibrosis induced by UUO or uIRI." (PMID 39495216, 2024). "In contrast, the global deletion of Sirt4 resulted in a remarkable reduction in the extent of renal fibrosis in all three kidney injury models." (PMID 39495216, 2024). "Importantly, the extent of renal fibrosis was remarkably augmented in mice injected with wtU2af2 OE and Sirt4 OE compared to that in wtU2AF2 OE mice." (PMID 39495216, 2024). "Our results showed that SIRT4 OE remarkably aggravated renal fibrosis under MSAB treatment." (PMID 39495216, 2024). "Collectively, these results suggest that Sirt4 deletion protects mice against renal fibrosis." (PMID 39495216, 2024). "Therefore, research is needed to further explore the role and mechanisms of SIRT4 in renal fibrosis, as well as potential therapeutic strategies." (PMID 39495216, 2024). "Therefore, the up regulation of SIRT1, SIRT3 and SIRT4 and downregulation of Claudin 1 by MR extract might prevent renal fibrosis by suppressing mitochondrial oxidative stress and the production of inflammatory cytokines." (PMID 35956936, 2022). "Exosomes containing αSRIT4 effectively inhibited renal fibrosis in UUO mice, accompanied by a decrease in SIRT4 expression in the nucleus, with little effect on mitochondria SIRT4 content." (PMID 39495216, 2024). "To determine whether S4KO alleviates renal fibrosis by upregulating the acetylation of U2AF2 in mouse kidney, we crossed Cdh16-cre/ERT2×U2af2flox/flox (U2af2-/-) with Sirt4-/- mice to generate DKO mice and then performed UUO surgery." (PMID 39495216, 2024). "Additionally, a recent study shows that Sirt4 could also translocate into nucleus, which mediates deacetylation of U2AF2 to modulate renal fibrosis." (PMID 40842073, 2025). "Furthermore, SIRT4 S36A or SIRT4 mNLS overexpression failed to accumulate SIRT4 in the nucleus and aggravated renal fibrosis in S4KO UUO mice." (PMID 39495216, 2024).
B cell lymphoma (4 papers, 2014 to 2023). "The positive expression of SIRT4 in B-cell lymphoma downregulates glutamine uptake and inhibits cell growth, whereas deletion of SIRT4 in the Eμ-myc models up-regulates glutamine consumption and accelerates tumorigenesis." (PMID 36982568, 2023). "Consistent with this hypothesis, SIRT4-deficient mice spontaneously develop a wide spectrum of tumors, and the absence of SIRT4 can accelerate cellular growth in MYC-induced B-cell lymphomas." (PMID 25085992, 2014).
Burkitt lymphoma (4 papers, 2018 to 2022). A rare form of malignant mature B-cell non-Hodgkin lymphoma. "Indeed, SIRT4 seems to have a tumor-suppressor role similar to that of SIRT3, as SIRT4-null mice develop lung tumors, loss of SIRT4 accelerates tumor progression in a mouse Burkitt lymphoma model and SIRT4 expression is reduced in several types of human cancers." (PMID 30197878, 2018). "In Myc-driven human Burkitt’s lymphoma cells, SIRT4 overexpression inhibits mitochondrial glutamine metabolism which, in turn, inhibits cell proliferation." (PMID 33585187, 2020). "The synergistic effect of SIRT4 and glycolysis inhibition leads to the death of Burkitt’s lymphoma cells." (PMID 33585187, 2020). "In human Burkitt lymphoma cells, the overexpression of SIRT4 repressed glutamine metabolism and glutamine-dependent cell proliferation, as observed in cells treated with glycolysis inhibitors, promoting cell death." (PMID 30666234, 2018). "Interestingly, in murine models with Burkitt lymphoma, the SIRT4 knockout resulted in accelerated lymphomagenesis and increased mortality." (PMID 35267521, 2022). "SIRT4 expression in Burkitt’s lymphoma cells does not affect expression of Myc and its target genes, which is incompatible with the effects seen in HCC cells and PC cells." (PMID 33585187, 2020). "Additionally, SIRT4 suppressed Burkitt lymphoma driven by c-Myc, independent of c-Myc activity." (PMID 30666234, 2018).
diabetes (4 papers, 2014 to 2025). "Such Sirt4 modulators would be excellent tools for physiological studies and lead compounds for drug development, for example for diabetes treatment." (PMID 29138502, 2017). "But SIRT4 functions in a negative way in diabetes development." (PMID 30559718, 2018). "Conversely, SIRT4 and SIRT7 exhibited negative effect on diabetes therapy, such as aggravating lipogenesis, and inhibiting insulin secretion." (PMID 30559718, 2018).
endothelial dysfunction (4 papers, 2020 to 2025). In vascular diseases, endothelial dysfunction is a systemic pathological state of the endothelium (the inner lining of blood vessels) and can be broadly defined as an imbalance between vasodilating and vasoconstricting substances produced by (or acting on) the endothelium. "SIRT4 was shown to prevent endothelial dysfunction and to repress inflammatory processes in response to cellular stress." (PMID 32796661, 2020). "Hypoxic downregulation of SIRT4 might lead to mitochondrial uncoupling, hence endothelial dysfunction, and ADP/ATP-translocase 2 (ANT2)-inhibition." (PMID 32796661, 2020). "Although the expression of SIRT4 is significantly reduced in an LPS-induced endothelial dysfunction model, SIRT4, unlike other sirtuins, primarily functions as a histone ADP-ribosyltransferase but lacks NAD-dependent deacetylase activity." (PMID 34445236, 2021).
esophageal cancer (4 papers, 2019 to 2025). A primary or metastatic malignant neoplasm involving the esophagus. "Low SIRT4 expression is associated with poor pathological grading and other clinical and pathological parameters in gastric, colon, liver, lung, and esophageal cancers." (PMID 31817470, 2019). "Many previous studies have identified SIRT4 as a tumor suppressor 16, 37, although there were reports indicating that SIRT4 was upregulated in several cancer tissues such as breast and esophageal cancer 19, 20, and it was required for cell survival during oncogene-induced transformation." (PMID 40384857, 2025). "Similarly, low levels of the SIRT4 protein are correlated with a poor prognosis in colon, lung, and esophageal cancers." (PMID 31817470, 2019).
fibrosis (4 papers, 2020 to 2024). the formation of excess fibrous connective tissue in an organ or tissue in a reparative or reactive process. "The tubulointerstitial fibrosis was alleviated by global deletion or tubular epithelial cell (TEC)-specific knockout of Sirt4, and aggravated by adeno-associated virus-mediated SIRT4 overexpression in TECs." (PMID 39495216, 2024). "Then, the immunochemistry result demonstrated that expression of SIRT4 was down‐regulated in the liver sample from patients with fibrosis." (PMID 34272822, 2021). "EX‐527, as a SIRT1‐selective inhibitor, relieve hepatic fibrosis by up‐regulating SIRT4 expression." (PMID 34272822, 2021). "However, the specific mechanism by which SIRT4 regulates renal fibrosis remains unclear." (PMID 39495216, 2024).
Myocardial fibrosis (4 papers, 2021 to 2025). "SIRT4 promotes cardiac dysfunction caused by myocardial fibrosis and hypertrophy by increasing ROS levels in response to pathological stimuli." (PMID 36760798, 2022). "However, Sirt4 deficiency improves cardiac function and reduces myocardial fibrosis through cardiomyocyte proliferation, showing a remarkable pro‐repair response." (PMID 40842073, 2025). "Furthermore, Sirt4 deficiency improved cardiac function and reduced myocardial fibrosis after ischaemia–reperfusion injury in adult mice." (PMID 40842073, 2025).
atherosclerosis (3 papers, 2022 to 2025). A disease characterized by the build-up of fatty material and calcium deposition in the arterial wall resulting in partial or complete occlusion of the arterial lumen. "In contrast with the findings of previous studies, other authors have shown that SIRT4 deficiency exacerbates inflammation and promotes the development of atherosclerosis, activating the phosphorylation of NF-κB." (PMID 38331795, 2024). "Atherosclerosis is caused by Sirt4 deficiency, which stimulates the NF-κB/IκB/CXCL2/3 pathway." (PMID 41567643, 2025). "It cannot deny SIRT4 as a potential target for developing valuable medicines to prevent or treat atherosclerosis, but the feasibility of SIRT4 as a therapeutic target still needs more research to explore." (PMID 35677446, 2022). "Several studies have identified a protective role of SIRT4 in atherosclerosis." (PMID 35677446, 2022).
breast tumor (3 papers, 2015 to 2020). "This study is to identify a mechanism linking decreased SIRT4 expression to breast tumor-initiating cells (BTICs) regulation and cancer progression." (PMID 32863939, 2020). "Such an inverse expression pattern of these two proteins can be confirmed by Pearson correlation analysis (R=−0.5908) and further reflects that CtBP negatively regulates SIRT4 expression in human breast tumor tissues." (PMID 25633289, 2015). "Besides, immunoblotting and immunohistochemistry staining also showed a significant decrease in SIRT4 protein levels in breast tumor tissues." (PMID 32863939, 2020). "Thus, excessive expression of SIRT4 considerably decreased the number of breast tumor-initiating cells." (PMID 32863939, 2020). "Besides, immunoblotting and IHC staining also showed a significant decrease in SIRT4 protein levels in breast tumor tissues." (PMID 33585187, 2020). "Our data illustrate that SIRT4 negatively regulates SIRT1 expression in breast tumors." (PMID 32863939, 2020). "SIRT4 can inhibit the self-renewal and expansion of breast tumor-initiating cells and may protect mice from breast tumors and lung metastasis by preventing the formation of mammary stem cells." (PMID 33585187, 2020). "Next, we determined the expression pattern of SIRT4 and CtBP in human breast tumor samples." (PMID 25633289, 2015).
Coronary Artery Disease (3 papers, 2014 to 2022). "Circulating levels of sirtuin 4, a potential marker of oxidative metabolism, is related to coronary artery disease in obese patients suffering from NAFLD, with normal or slightly increased liver enzymes." (PMID 35206342, 2022).
glioblastoma (3 papers, 2023 to 2025). The most malignant astrocytic tumor (WHO grade IV). "Hexokinase II (HKII), lactate dehydrogenase A (LDHA), sirtuin 4 (SIRT4), and glutamine synthetase (GS) have been shown to be elevated in glioblastomas." (PMID 36768856, 2023). "However, SIRT4 protein expression was elevated in the U87 glioblastoma cell line compared with immortalized human astrocytes." (PMID 40710366, 2025).
heart failure (3 papers, 2022 to 2025). Inability of the heart to pump blood at an adequate rate to meet tissue metabolic requirements. "In response to pathogenic activation, Sirt4 raises ROS levels, which causes hypertrophic growth, the development of fibrosis, and heart failure." (PMID 41567643, 2025). "However, a report suggests a RONS-driven mechanism of heart failure development, mediated by SIRT4, though that study requires further validation." (PMID 41516053, 2025). "Compared to SIRT1, SIRT3, and SIRT6, studies on SIRT2,541 SIRT4, SIRT5,542 and SIRT7 in heart failure are limited." (PMID 36581622, 2022). "Studies on SIRT2, SIRT4, SIRT5, and SIRT7 might reveal promising research directions for the treatment of heart failure." (PMID 36581622, 2022). "However, the antioxidant properties of SIRTs should not be overgeneralized, as SIRT4 overexpression was recently found to accelerate heart failure development under pressure overload, primarily by enhancing profibrotic transcriptional signaling through RONS-driven mechanisms." (PMID 41516053, 2025).